Y_RNA (Y RNA )
Gene: Miscellaneous RNA gene on chromosome 11 (75,837,544 to 75,837,645, reverse strand). Ensembl gene ENSG00000199362.
Homologues: Orthologues: chimpanzee Y_RNA (100% identical), macaque Y_RNA (97% identical). Paralogues in human: Y_RNA (87% identical), RNY3 (86% identical), Y_RNA (86% identical), Y_RNA (85% identical), Y_RNA (84% identical), RNY3P1 (83% identical), Y_RNA (83% identical), RNY3P2 (82% identical), RNY3P4 (82% identical), Y_RNA (82% identical), RNY3P13 (81% identical), RNY3P16 (81% identical), and 97 more.